ACTN2 (actinin alpha 2)
Diseases named in the same sentence as ACTN2 in open-access papers (continued):
Sharing a sentence is not in itself a finding about the gene and the disease.
aneurysm (2 papers, 2023 to 2025). Bulging or ballooning in an area of an artery secondary to arterial wall weakening. "Although ACTN2 mutation was associated with cardiac and peripheral vascular disease occurrence, to the best of our knowledge, the present case is the first report of a visceral (splenic) aneurysm directly linked with this rare mutation." (PMID 37510845, 2023). "Firstly, the clinical relevance of ACTN2 in different aneurysm subtypes (such as intracranial aneurysms and aortic aneurysms) requires further validation in large-scale cohorts." (PMID 40881324, 2025). "We explored the regulatory mechanisms of ACTN2 in aneurysms through epigenetic and transcriptional analyses." (PMID 40881324, 2025). "We hypothesize that low expression of PRDM9 inhibits H3K4me3, thereby reducing ACTN2 expression and subsequently affecting the progression of aneurysms." (PMID 40881324, 2025). "We hypothesized that low-expression PRDM9 suppressed H3K4me3, leading to reduced ACTN2 expression and contributing to aneurysm progression." (PMID 40881324, 2025). "This study reveals that PRDM9 regulates ACTN2 expression through epigenetic modifications and interacts with PDLIM1 to mediate VSMC function and aneurysm progression." (PMID 40881324, 2025). "Therefore, the ACTN2-PDLIM1-Hippo axis may serve as a central hub in the progression of aneurysms." (PMID 40881324, 2025). "We investigated the downstream targets of ACTN2 and their roles in VSMC function and aneurysm progression." (PMID 40881324, 2025).
atrial fibrillation (2 papers, 2019 to 2021). A disorder characterized by an electrocardiographic finding of a supraventricular arrhythmia characterized by the replacement of consistent P waves by rapid oscillations or fibrillatory waves that vary in size, shape and timing and are accompanied by an irregular ventricular response. "The ACTN2 variant p.Met228Thr was identified in an Italian family with atypical HCM and early onset atrial fibrillation (AF) by next generation sequencing." (PMID 33802723, 2021).
muscular dystrophy (2 papers, 2020 to 2021). Muscular dystrophy (MD) refers to a group of more than 30 genetic diseases characterized by progressive weakness and degeneration of the skeletal muscles that control movement. "In mammals, ACTN2 is highly expressed in skeletal and cardiac muscle and mutations in ACTN2 cause cardiac myopathy and muscular dystrophy in humans." (PMID 34795696, 2021).
Skeletal myopathy (2 papers, 2022 to 2025). "Five studies reported eight causative ACTN2 variants in patients with a skeletal muscle disorder, including seven heterozygous mutations with de novo occurrence or dominant disease inheritance, and one homozygous mutation with recessive disease transmission." (PMID 36116040, 2022). "Moreover, based on our findings, it is currently not possible to identify clear hallmarks of ACTN2‐related cardiac and skeletal myopathy." (PMID 36116040, 2022).
ventricular fibrillation (2 papers, 2023). A disorder characterized by an electrocardiographic finding of a rapid grossly irregular ventricular rhythm with marked variability in QRS cycle length, morphology, and amplitude. "Our study identifies A868T as a possible pathogenic variant of ACTN2 in cardiac muscle that leads to severe ventricular fibrillation and an HCM-like phenotype with diastolic dysfunction." (PMID 37834023, 2023).
dental caries (1 paper, 2013). The decay of a tooth, in which it becomes softened, discolored, and/or porous. "To further examine whether the association of this gene set with dental caries is driven by gene ACTN2, we excluded this gene and performed the same gene set analysis using the mixed model approach." (PMID 23967329, 2013). "These dental caries GWA studies identified several loci and genes, such as ACTN2, LYZL2, and AJAP1." (PMID 23967329, 2013).
diabetic cardiomyopathy (1 paper, 2025). Diabetic cardiomyopathy is a disorder of the heart muscle in people with diabetes. "Sciatic nerve proteomics showed a significant increase in LRP group myosin, TNN13, MYL7, MYL3, TNNC, MYBPC2, ACTN2, and KEGG enrichment analyses showed that these proteins were mainly enriched in pathways such as cardiac contraction, diabetic cardiomyopathy, and dilated heart disease." (PMID 40321612, 2025).
hepatoma (1 paper, 2023). "For example, ACTN2 overexpression in human hepatoma cells shows an enhanced cell viability and invasion, suggesting that it may play a role in late metastasis, such as exosmosis and lung colonization." (PMID 36984779, 2023).
hereditary cardiomyopathies (1 paper, 2024). "CAPN1 had heart enhanced interactions with ACTC1 and ACTN2, which participate in the formation of the actin cytoskeleton and are previously associated with hereditary cardiomyopathies." (PMID 38848015, 2024).
idiopathic ventricular fibrillation (1 paper, 2014). "The diverse clinical phenotypes seen in this family, including idiopathic ventricular fibrillation, LVNC, and sudden unexplained death, suggest mutations in the ACTN2 gene likely perturb a number of different mechanical and arrhythmogenic substrates." (PMID 25224718, 2014).
intracranial aneurysms (1 paper, 2025). "The regulatory mechanism of ACTN2 in intracranial aneurysms (IA) has not yet been fully elucidated." (PMID 40881324, 2025).
liver cancer (1 paper, 2021). An epithelial or non-epithelial malignant neoplasm that arises from the liver. "For example, the overexpression of ACTN2 in human liver cancer cells enhanced cellular motility and invasion abilities which suggested it could be functional in liver cancers’ metabolism." (PMID 34116652, 2021).
malocclusion (1 paper, 2025). "Candidate genes such as COL1A2, matrix metalloproteinases (MMP-1, MMP-9), and muscle-related genes (ACTN2, ACTN3) have been implicated in craniofacial morphology and malocclusion risk." (PMID 41153339, 2025).
microphthalmia (1 paper, 2018). Congenital or developmental anomaly in which the eyeballs are abnormally small. "Interestingly, Actn2 knockdown in zebrafish results in lens defects and microphthalmia." (PMID 29565969, 2018).
muscle atrophy (1 paper, 2023). The loss of muscle tissue due to inactivity or disease. "The expression level of sarcomeric protein actinin Alpha 2 (ACTN2) also decreased in the tibialis anterior (TA), gastrocnemius (GA), and diaphragm of Δ7-SMA mice, which is a hallmark of skeletal muscle atrophy." (PMID 36604149, 2023).
myocardial infarction (1 paper, 2022). Gross necrosis of the myocardium, as a result of interruption of the blood supply to the area, as in coronary thrombosis. "It was found that FBs were proliferated in the site of myocardial infarction and Actn2 was colocalized with Vimentin." (PMID 35203611, 2022).
papillary thyroid carcinoma (1 paper, 2015). "A gene profiling study has shown that Actn2 is over-expressed in oncocytic and papillary thyroid carcinoma." (PMID 26580608, 2015).
proteopathy (1 paper, 2022).
retinitis pigmentosa (1 paper, 2017). Retinitis pigmentosa (RP) is an inherited retinal dystrophy leading to progressive loss of the photoreceptors and retinal pigment epithelium and resulting in blindness usually after several decades. "It seems to take part in the same pathway as ACTN2, which in turn physically interacts with TTC8, often related to BBS and retinitis pigmentosa (Genemania)." (PMID 28800606, 2017).
Sepsis (1 paper, 2022). Sepsis is defined as life-threatening organ dysfunction caused by a dysregulated host response to infection. "Based on degree centrality, 27 hub genes were selected, in which six genes (MMP9, CD44, EGR1, ACTN2, TNNT3, and PTGS2) were selected on the basis of a multi-network variable selection approach and validated in a well-established sepsis mice model." (PMID 35205254, 2022).
Stroke (1 paper, 2025). Sudden impairment of blood flow to a part of the brain due to occlusion or rupture of an artery to the brain. "Nine days post-stroke, proteins annotated as thin filaments were upregulated, including Ablim1, Dbnl, Parvb, Capg, and Pdlim3; Actn2, Pdlim7, Tpm1, and cofilin 2 (Cfl2) were downregulated." (PMID 41226396, 2025). "In the current study, Actn2 expression was upregulated on the 3rd day after stroke, while Actn3 was downregulated." (PMID 41226396, 2025).
myopathy (13 papers, 2013 to 2025). A disease of the muscle in which the muscle fibers do not function properly. "Our results show a growing body of clinical, genetic, and functional evidence, which underlines the central role of ACTN2 in the muscle tissue and myopathy." (PMID 36116040, 2022). "On the other hand, the association between ACTN2 mutations and myopathy is supported by a mounting body of clinical, genetic, and functional evidence." (PMID 36116040, 2022). "Further, we investigated the functional characterization of this mutation, together with the previously reported mutations in ACTN2‐related myopathy, providing insightful information to clarify the molecular mechanisms underlying." (PMID 34170073, 2021). "In one family, a pathogenic ACTN2 variant induced core myopathy with jagged z-lines." (PMID 38982518, 2024). "The downregulation of the ACTN2 gene in women with GDiM, in comparison to continent–diabetic women, may be linked to the development of myopathy." (PMID 36361671, 2022). "Thus, the various phenotypes and limited mutations in ACTN2‐related myopathy make the genotype‐phenotype correlation hard to understand." (PMID 34170073, 2021). "Correspondingly, canonical MEF2 target genes linked to myopathy and contractile function, including TNNT2, MYH7, ACTN2, and ACTA1, were also restored upon HDAC5 silencing." (PMID 41283336, 2025). "Our results expanded the phenotypes of ACTN2‐related myopathy and provided helpful information to clarify the molecular mechanisms." (PMID 34170073, 2021). "However, limited segregation and functional data are available to support the pathogenicity of most previously reported missense variants and clear‐cut genotype‐phenotype correlations are currently only demonstrated for some ACTN2‐related myopathies." (PMID 36116040, 2022). "Therefore, additional patients with ACTN2‐related myopathy are important to investigate the clinical features and more functional studies are needed to clarify the molecular mechanisms." (PMID 34170073, 2021). "Until now, there is only one report linking ACTN2 to myopathy." (PMID 33802723, 2021). "Since most core diseases are caused by RYR1 variants, it may also be another target in excitation‐contraction coupling for the studies of ACTN2‐related myopathy." (PMID 34170073, 2021). "While useful to prove causation, this approach did not recapitulate the non-muscle features of ACTN2-related myopathy such as kyphoscoliosis." (PMID 31874912, 2019).
tumor (8 papers, 2015 to 2025). "To explore the functions of ANG–ACTN2 interaction, we analyzed cell migration and invasion, as well as cell proliferation and survival with tumor cells, by overexpressing the segment of ACTN2-383–632." (PMID 35463945, 2022). "Overloaded ACTN2 383–632 can interfere with tumor cell migration, invasion, cell proliferation, and survival." (PMID 35463945, 2022). "In this study, we identified the binding domains and sites in ANG and ACTN2 and evaluated the function of this interaction in tumor cell behaviors." (PMID 35463945, 2022). "In functional analysis, overexpressed ACTN2-383–632 could impair tumor cell motility observably, including cell migration and invasion." (PMID 35463945, 2022). "Meanwhile, we employed Matrigel-coated transwell invasion assay to find whether tumor cell invasion could also be inhibited by ACTN2-383–632 segment overexpression." (PMID 35463945, 2022). "Meanwhile, ACTN2-383–632 overexpression inhibited tumor cell proliferation and survival as well." (PMID 35463945, 2022). "Similarly, overexpression of an ACTN2 fragment suppresses tumor cell motility and proliferation." (PMID 40941396, 2025). "Thus, in the present study, we employed Y2H and glutathione-S-transferase (GST) pull-down assay to further identify the binding domains and sites of these two proteins, respectively, and evaluated the function of ANG/ACTN2 interaction in tumor cell proliferation and motility." (PMID 35463945, 2022). "The two hypomethylated hub genes, CTLA4 and CDSN, were significantly upregulated, and two hypermethylated hub genes, ACTN2 and MYH11, were downregulated in the HNSC tumor samples." (PMID 35096593, 2021). "When the segment ACTN2 383–632 is overloaded, the functions of ANG and ACTN2 would be disrupted, such as cell proliferation, survival, and migration, which results in angiogenesis or tumor growth inhibition." (PMID 35463945, 2022). "In addition, we also verified four hub genes (CTLA4, CDSN, ACTN2, and MYH11) that their expression levels in tumor tissue might be regulated by the mechanism of DNA methylation." (PMID 35096593, 2021).
cardiac diseases (7 papers, 2014 to 2024). "Many unique, rare ACTN2 variants have been identified in patients with cardiac diseases." (PMID 36116040, 2022). "Finally, many additional ACTN2 variants have been identified in large sequencing projects focused on cardiac diseases." (PMID 36116040, 2022). "The protein product of PDLIM3 is predicted to interact with the protein products of several other genes that are linked with heart disease, including MYBPC3, ACTN2, and CAV3." (PMID 32013268, 2020). "For four of these loci, the top gene according to OPEN had been shown to be mutated in DCM (PLN, ACTN2, TNNT2, TTN), while for two others, the top gene was known to be mutated in HCM (MYL2) or an arrhythmogenic form of cardiac disease (CASQ2)." (PMID 25633252, 2014).
cancer (6 papers, 2016 to 2025). A tumor composed of atypical neoplastic, often pleomorphic cells that invade other tissues. "Regarding the remaining DEPs, Myh4, Acta1, Tnnt3, Mb, Ttn, Actn2, Myh7, Myl1, Mybpc2, Myl3, and Tnnc2 are associated with several cancers." (PMID 39861068, 2024). "In humans, mutations in the ACTN2 gene cause dilated cardiomyopathy; however, the exact function of α-Actinin-2 in the development of cancer is largely unknown." (PMID 37337244, 2023). "In this study, we report our findings on ACTN2 gene, which showed that its expression was specifically increased in cancer tissues from HAGC with diffuse BMM, compared to NAGC and data from The Human Protein Atlas dataset." (PMID 37337244, 2023). "Five cancer genes mutated at greater frequency in AA LUAD tumors (MAX, ACTN2, PRKD1, PTPRC, STK11) remained significant after accounting for mutation burden and age at diagnosis." (PMID 32952607, 2020).
cardiovascular diseases (1 paper, 2025). "Previous studies have demonstrated that ACTN2 is involved in the regulation of cardiovascular diseases, such as myocardial hypertrophy and atherosclerosis." (PMID 40881324, 2025). "Research has shown that PRDM9 plays a pivotal role in cardiovascular diseases, but whether it regulates ACTN2 expression in IA via methylation modification remains unclear." (PMID 40881324, 2025).
renal disorders (1 paper, 2015). "Missense mutations in ACTN1, ACTN2 and ACTN4 cause dominantly inherited platelet, cardiac and renal disorders respectively, while a nonsense mutation in ACTN3 seems to have been beneficial during the recent evolution of some human populations." (PMID 26312134, 2015).
ACTN2 also shares sentences with these, for which no sentence is quoted: Arrhythmia (3 papers); infection (3); breast carcinoma (2); invasive ductal carcinoma (2); prostate carcinoma (2); viral infection (2); aortic aneurysm (1); aortic stenosis (1); atypical atrial flutter (1); autosomal recessive inherited disease (1); bladder urothelial carcinoma (1); cardiac arrhythmia (1); cholangiocarcinoma (1); chronic myelogenous leukemia (1); colon adenocarcinoma (1); Danon disease (1); embryonal carcinoma (1); fibrosis (1); focal segmental glomerulosclerosis (1); Hearing impairment (1); homocystinuria (1); hypertrophy (1); infectious disease (1); intrinsic cardiomyopathy (1); invasive breast carcinoma (1); kidney chromophobe (1); left ventricular hypertrophy (1); left ventricular noncompaction (1); Left ventricular noncompaction cardiomyopathy (1); lung adenocarcinoma (1).
A further 14 diseases each share a sentence with ACTN2 in 1 paper.